HSPA4 (heat shock protein family A (Hsp70) member 4)
Diseases named in the same sentence as HSPA4 in open-access papers (continued):
Sharing a sentence is not in itself a finding about the gene and the disease.
cancer (continued). "The six thermogenes include HSP90AA1 and HSPA4, common in thermoresistance and DAMPs/ICD, DNAJB5, the protein product of which has the highest estimated thermostability, and HSPA1A, HSP90AB1, and BAG1, which are implicated in cancer-relevant pathways (underlined)." (PMID 31814876, 2019). "Heat shock protein family A member 4 (HSPA4), a member of the HSP70 family, is known to be involved in the progression of various cancers." (PMID 39599898, 2024). "Elevated expression of HSPA4 and HSP90AA1 is related with poor clinical outcomes in cancer patients." (PMID 37033966, 2023). "The expressions of five HSPs members (HSPH1, HSPD1, SERPINH1, HSPA4 and HSP90AA1) in more than 20 types of cancers were detected and compared with expressions in normal tissues using the ONCOMINE database." (PMID 32523426, 2020). "Despite a multitude of studies examining HSPA4’s role in specific cancer types, a holistic perspective remains lacking." (PMID 38305786, 2024). "Previous studies have largely focused on individual cancer types, lacking a comprehensive understanding of HSPA4’s overall role." (PMID 38305786, 2024). "Crucially, upon evaluating genes that may significantly influence cancer prognosis, HSP90AA1, HSPA8, DNAJB1, and HSP90AB1 manifested pronounced correlations with HSPA4 expression." (PMID 38305786, 2024). "Moreover, the expression patterns of the thermogenes HSPA4 and HSP90AA1 and the oncogene PLK1 were found to be positively correlated in diverse types of cancers." (PMID 31814876, 2019). "Also, we found that the expression levels of HSPA4 and HSP90AA1 and the detox enzyme gene CAT (catalase) are positively correlated in cancer." (PMID 31814876, 2019). "The HSPA4/HSPA14 axis induces the migration, invasion, and transformation of cancer cells." (PMID 25379943, 2014). "However, despite numerous studies on HSPA4 in specific cancer types, a comprehensive analysis across all cancer types is lacking." (PMID 38305786, 2024). "HSPA2 and HSPA4 did not seem to be affected in different types of cancer." (PMID 34692733, 2021).
infection (4 papers, 2015 to 2024). The state of being infected such as from the introduction of a foreign agent such as serum, vaccine, antigenic substance or organism. "The results of the Western blot and gray scale analysis showed that BoHV-1 or BPIV3 infection promoted HSPA4 expression." (PMID 39599898, 2024). "The virus titer results demonstrated that HSPA4 overexpression facilitated BRSV replication at different infection doses." (PMID 39599898, 2024).
gastrointestinal tumors (1 paper, 2024). "However, the precise molecular mechanisms underlying the association between gastrointestinal tumors and HSPA4 require further investigation to elucidate." (PMID 38305786, 2024). "Previous studies also indicate that HSPA4 plays a pivotal role in these gastrointestinal tumors." (PMID 38305786, 2024). "Furthermore, we hypothesize that the link between HSPA4 and gastrointestinal tumors might be closely related to changes in the TME’s stress response, including reduced glucose and oxygen availability and environmental acidification." (PMID 38305786, 2024).
heart diseases (1 paper, 2022). "We therefore propose that genetic screening by Hspa4 gene sequencing could identify novel mutations and expand the spectrum of myopathy-associated genes in patients with inherited skeletal muscle myopathies and/or pediatric heart diseases." (PMID 35568953, 2022).
inflammation (1 paper, 2017). Aberrant reaction of the microcirculation characterized by movement of fluid and leukocytes from the blood into extravascular tissues. "Interestingly, such increased expression of HSPA4 was accompanied by that of gankyrin, which suggests possible involvement of ganlyrin in the development of long-standing colonic inflammation." (PMID 28160571, 2017).
myopathy (1 paper, 2022). A disease of the muscle in which the muscle fibers do not function properly. "It remains to be addressed whether myopathy patients with genetically unknown cause carry Hspa4 mutations." (PMID 35568953, 2022). "Hspa4-KO mice that survive the first month of life develop a progressive myopathy, characterized by centrally nucleated myofibers, heterogeneous myofiber size distribution and inflammatory cell infiltrates, associated with defective autophagy and increased apoptotic cell death." (PMID 35568953, 2022). "In conclusion, we demonstrate that the deletion of HSPA4 in skeletal muscle leads to a progressive generalized myopathy, highlighting the critical role of HSPA4 in regulating the genetic repertoire required for the appropriate maintenance of skeletal muscle integrity." (PMID 35568953, 2022).
HSPA4 also shares sentences with these, for which no sentence is quoted: Azoospermia (2 papers); colon cancer (2); malaria (2); pancreatic cancers (2); allergic rhinitis (1); asthenozoospermia (1); bladder cancer (1); chronic lymphocytic leukemia (1); Cognitive impairment (1); endothelial dysfunction (1); falciparum malaria (1); gestational diabetes (1); Glucose intolerance (1); gynecological tumors (1); Headache (1); invasive carcinoma of the breast (1); metastatic tumors (1); neuritis (1); neurodegenerative disease (1); oral cancer (1); Parkinson’s (1); posterior subcapsular cataracts (1); quadriplegia (1); rectal cancer (1); Sepsis (1); Skeletal myopathy (1); squamous cell carcinoma (1); status epilepticus (1); thymic carcinoma (1); uterine cancer (1).
A further 1 disease shares a sentence with HSPA4 in 1 paper.